IL6 (interleukin 6)
Diseases named in the same sentence as IL6 in open-access papers (continued):
Sharing a sentence is not in itself a finding about the gene and the disease.
dementia (continued). "Consistent with our findings, Mucispirillum is reduced in mice with disrupted cognition and has been reported to be negatively correlated with cognitive abilities and positively correlated with IL‐6 (pro‐inflammatory cytokine) levels in the brain cortex of the SAMP8 mouse model of dementia." (PMID 41524247, 2026). "In one longitudinal community study assessing the relationship between chronic stress (caring for a spouse with dementia) and IL-6 production, it was observed that the average increase in IL-6 levels in caregivers was approximately four times higher than in noncarers." (PMID 40313235, 2025). "Interestingly, elevated markers of systemic inflammation (such as IL-6 and CRP) have been linked to increased dementia risk, even decades prior to its occurrence, possibly due to accelerated accumulation of amyloid-β." (PMID 41403901, 2025). "Examination of the highlighted keywords revealed the commonality between HF and dementia, namely IL6, ACE, APOE, APP, ADIPOQ, LEP, and NPPB, suggesting that these proteins may link the two pathologies." (PMID 40699836, 2025). "Several studies have shown that elevated levels of IL-6 increase the risk of cognitive and memory decline, even in individuals without a dementia diagnosis." (PMID 40004217, 2025). "High levels of IL6 and CRP in plasma are a risk factor for dementia." (PMID 40699836, 2025). "Conversely, among older persons without dementia, higher IL-6 levels are linked to reduced brain volume, but not WMH volume." (PMID 38414630, 2024). "This theory proposes that IL-6 may play a role in brain tissue reactivity among dementia patients by promoting neuroinflammation." (PMID 39104536, 2024). "Elevated levels of circulating inflammatory markers such as IL-6, TNFα and CRP, induces the development of chronic low-grade inflammation which has been identified as a risk predictor for several diseases such as T2DM and dementia." (PMID 37720640, 2023). "Meta‐analyses of relatively large samples across multiple countries have demonstrated associations between a limited number of peripheral inflammatory biomarkers including CRP and IL‐6 among others and all‐cause dementia, but not AD dementia." (PMID 37584418, 2023). "Patients with dementia who nap longer were found to have higher IL-6 levels." (PMID 35898322, 2022). "Furthermore, severity of dementia in the course of AD is positively correlated with IL-6 concentration in serum." (PMID 36045741, 2022). "Studies have shown that IL-1 and IL-6 levels are significantly positively correlated with MMSE scores in patients with dementia, suggesting that IL-1and IL-6 are closely associated with the development of dementia." (PMID 36304171, 2022). "Prior studies have suggested that IL-6 trans-signaling may contribute to the pathogenesis of neurodegenerative conditions, such as dementia." (PMID 36405620, 2022). "Some studies have suggested that high levels of IL-6 during pregnancy may be related to working memory dysfunction and dementia in offspring later in life." (PMID 34684531, 2021). "In support of this mechanism, evidence from a growing number of longitudinal studies suggests that markers of systematic inflammation, such as tumor necrosis factor, nitric oxide synthase, and interleukin IL-1β, IL-6, and IL-18, are involved in the pathogenesis of dementia." (PMID 32651320, 2020). "In the case of leptin, as compared to adiponectin, the opposite direction of correlations with the same parameters were stated in all-cause dementia i.e. positive correlation with BMI, fasting glucose, insulin, HOMA-IR, IL-6 and hsCRP and positive correlation with HDL-C." (PMID 28421328, 2017). "Significantly higher levels of IL-6 concerned dementia with vascular component (VaD and MD)." (PMID 28421328, 2017).
dementia (continued). "Linking familial risks with early plasma indicators of AD and dementia (C-reactive protein, interleukin-6 and α1-antichymotrypsin, for example) with plasma DHA status may also help to identify those with the most potential for benefit from supplementation." (PMID 26901223, 2016). "IL-6 and IL-8 have been found in the CSF of patients with HIV-1 associated dementia (HAD), suggesting that they might play important roles in HIV-1 neuropathology." (PMID 26075907, 2015). "In addition, inhibiting the expression of TLR4, a receptor on microglia, reduces microglial activation and the release of inflammatory cytokines, including IL-6, TNF-α, and IL-1β, alleviating the chronic neuroinflammation associated with AD and other dementias." (PMID 40872491, 2025). "In addition, it has been shown that IL-6 is regulated by estrogen, suggesting that elevated IL-6 levels may contribute to neuroinflammation and dementia particularly in women." (PMID 38075266, 2023). "In addition, dementia can be also correlated to high levels of systemic IL6." (PMID 37446262, 2023). "Moreover, preclinical studies and clinical trials are required to investigate whether anti-IL-6 drugs, such as tocilizumab, are able to improve cognitive function in normal aging and in dementia." (PMID 36915478, 2023). "Thus, elevated serum IL-6 levels can be used to differentiate dementia from normal aging." (PMID 37446262, 2023). "The CRP and IL-6 were associated with all-cause dementia rather than AD." (PMID 36293430, 2022). "Furthermore, we analyzed the association between IgG N-glycome and markers of inflammation including anti-inflammatory (IL-4 and IL-10) as well as proinflammatory factors (CRP, TNF-α, IFN-γ, IL-1β, and IL-6), contributing to explain the role of IgG glycosylation on dementia." (PMID 33542243, 2021). "While prolonged and exacerbated IL-6 exposure is associated with inflammatory processes and numerous chronical disease such as dementia, it is not clear whether IL-6 is the cause or only a marker of disease." (PMID 34823469, 2021). "In previous studies, elevated peripheral vascular cell adhesion molecule-1, tumor necrosis factor (TNF)-α, IL-2, IL-6, IL-18, and interferon-γ were found in patients with mild AD, suggesting that cytokine signaling might play a role in the intermediate stages of dementia." (PMID 35069588, 2021). "Moreover, in all-cause dementia obese patients compared to patients without abdominal obesity significantly higher levels of pro-inflammatory indices (IL-6 and hsCRP) and lower anti-inflammatory parameters (HDL-C) were observed." (PMID 28421328, 2017). "As it serves as one of the inflammatory triggers for the following reasons; IL-6 can be consistently detected in the brains of AD patients but not in the brains of nondemented elderly people, and increased IL-6 levels in serum have been shown to differentiate dementia from normal ageing." (PMID 25025046, 2014). "On the other hand, high concentrations of proinflammatory proteins in plasma may be a consequence of the dementia pathophysiology, because amyloid plaques induce the expression of cytokines, like IL-1 and IL-6, which increases the levels of peripheral proinflammatory proteins." (PMID 24587705, 2014). "Serum levels of IL-6, IL-8, and IFN-γ were significantly elevated at baseline in men that developed MCI and/or dementia 15 years later, compared to men that remained cognitively healthy." (PMID 41384827, 2025). "In clinical and pre-clinical models of dementia and AD, neuroinflammatory mediators such as the COX enzyme and pro-inflammatory cytokines, including TNF-α, IL-6, IL-1α, and IL-1β, trigger the nervous system’s inflammatory responses." (PMID 36840284, 2023). "Inflammatory markers, such as C-reactive protein (CRP) and interleukin-6 (IL-6), have been found to be elevated in individuals with MCI and dementia." (PMID 37509024, 2023).
dementia (continued). "Bacopa monniera decreases intra-neuronal protein aggregation and lipofuscin accumulation and prevents microglia from secreting pro-inflammatory cytokines (IL-6 and TNF-α) in aging and dementia models." (PMID 35893883, 2022). "Increased inflammatory markers such as soluble tumor necrosis factor receptor 2 (sTNFR2), interleukin-6 (IL-6), and monocyte chemoattractant protein-1 (MCP-1) have been reported in patients with dementia compared with controls." (PMID 35069588, 2021). "It is proved in the present study that expression levels of IL-6, CRP and TNF-α proteins in VD patients are higher than those in the normal population on one hand, and positive correlated to dementia degrees on the other hand." (PMID 34475939, 2021). "The release of cytokines, such as interleukin (IL)-6 and tumor necrosis factor (TNF)-α, by microglia play important roles in the pathogenesis of dementia." (PMID 31096580, 2019). "Previous findings have shown higher peripheral levels of inflammatory markers such as IL-6, CRP, TNF-α in patients with dementia compared to controls." (PMID 28798686, 2017). "Inflammatory cytokines such us interleukin (IL)-6, and hs-CRP (high sensitivity- chronic reactive protein) are also elevated in patients with dementia." (PMID 29088788, 2017). "Improving the sample size of the study is necessary to confirm the relationship between IL-6, Hs-CRP, and preclinical AD, such as memory impairment and MCI in middle-aged subjects and dementia in subjects with higher age." (PMID 26682220, 2015). "In comparison to other dementias (AD or CJD), MS and controls, we observed an elevated level of proinflammatory cytokines (IL-6, IL-13, TNF-α and G-CSF) specifically in the serum of rpAD patients." (PMID 25315814, 2014). "Decreased in patients with dementia. miR-223 level correlated with Mental State Examination (MMSE) scores, Clinical Dementia Rating (CDR) scores, magnetic resonance spectroscopy (MRS) spectral ratios, and serum concentrations of IL-1b, IL-6, TNF-α, and CRP." (PMID 40943171, 2025). "Since most of the identified proteins are not present in both diseases, we performed two independent PPI analyses: the first using the proteins associated with HF (NPPB, REN, ADIPOQ, VWF, ACE, IL6, and CRP) and the second using the proteins involved in dementia (CRP, APP, MAPT, APOE, ACE, and IL6)." (PMID 40699836, 2025). "We found that IL6, REN, CRP, and ACE play a role in dementia (purple spheres)." (PMID 40699836, 2025). "Furthermore, we measured C-reactive protein (CRP) and interleukin-6 (IL-6), well-established markers of systemic inflammation known to be elevated in POD and dementia." (PMID 40218194, 2025). "The coronavirus’s direct neuroinvasive capacity is uncertain, but potential mechanisms for inflammation involve cytokine interplay like interleukin-1 (IL-1) and interleukin-6 (IL-6), potentially collaborating with amyloid-induced type I interferon (IFN) in dementia." (PMID 38247982, 2024). "Inflammatory markers such as tumor necrosis factor (TNF), interleukin-6 (IL-6), chitinase-3-like protein 1 (CHI3L1 or YKL-40), and acute phase C reactive protein (CRP) were found to have effects on the brains or peripheral regions of dementia patients." (PMID 37873875, 2023). "Regarding the role of comorbidities relevant to the study’s outcomes, future studies should evaluate the presence of knee osteoarthritis and its effects on IL-6 levels and sleep quality in individuals with or without comorbid dementia." (PMID 37489445, 2023). "In addition to reversing cell cycle arrest, BM also reduced intra-neuronal protein aggregation and lipofuscin accumulation, and it prevented microglia from secreting pro-inflammatory cytokines (IL-6 and TNF-α) in aging and dementia models." (PMID 35893883, 2022). "Moreover, elevated concentrations of circulating pro-inflammatory cytokines (IL-1, IL-6, TNF-α) have been found in people suffering from dementia." (PMID 36045741, 2022).
dementia (continued). "Cell destruction by phagocytosis, membrane attack complex (MAC) by opsonizing component markers, as well as the proinflammatory cytokines (IL-1, IL6, TNF-α, and interferon-γ) produced by these innate immune responses affect the disease progression and severity of dementia." (PMID 33711047, 2021). "Present data are thus consistent with the original hypothesis that opening of the BBB by acute ischemic stroke may permit the elevated levels of IL-6 and CRP present in the brain tissue of dementia patients to be reflected in the serum." (PMID 32758167, 2020). "We observed that plasma IL-6, IL-8, and PAI-1 measured in the ED were significantly associated with prolonged ED delirium durations in patients without dementia admitted to the hospital." (PMID 31856187, 2019). "Our study highlights the changes and potential contributions of several chemokines (CXCL1, CCL3, CXCL5, CXCL6, CCL3, CCL19), interleukins (IL8, IL6-RA, IL18-BP), and other immune markers (OSM, ALCAM, OPG, CHIT1, YKL-40, STAMBP, MMP-9, MMP-10) in the prodromal and dementia phases of AD." (PMID 31694701, 2019). "The involvement of cytokines in dementia is supported by studies showing that the levels of pro-inflammatory cytokines [e.g., tumor necrosis factor alpha (TNF-α), interleukin (IL)-1α, IL-1β, IL-6, and IL-8] are altered." (PMID 30510525, 2018). "Values of log-transformed IL-6 in this subset of patients with DLB were also significantly lower than those of control subjects without dementia (p = 0.003)." (PMID 26434635, 2015). "The IL-6 levels were still significantly decreased in patients with DLB compared with both control subjects without dementia and patients with AD when the IL-6 values were analysed after age adjustment (ANCOVA)." (PMID 26434635, 2015). "Analysis of CSF from this subcohort still showed decreased levels of IL-6 in patients with DLB compared with control subjects without dementia (p = 0.003)." (PMID 26434635, 2015). "IL-6 levels were significantly higher in the CSF of patients with cerebrovascular disease with dementia compared with patients with cerebrovascular disease without dementia." (PMID 25177271, 2014). "In a study of older adults undergoing a chronic stressor (men and women who were caregiving for a spouse with dementia), Caregivers' average rate of increase in IL-6 was about four times as large as that of non-caregivers." (PMID 17374166, 2007). "Likewise, a study conducted with older individuals with mild-to-moderate dementia demonstrated that serum IL-6 was not altered after a 12-week sweet cherry juice (200 mL) consumption." (PMID 36771387, 2023). "Meanwhile, we investigate the associations between IgG N-glycan profiles and inflammation factors including anti-inflammatory (IL-4 and IL-10) and proinflammatory factors [IL-1β, IL-6, CRP, TNF-α, and interferon-gamma (IFN-γ)], which may further explain the role of IgG glycosylation in dementia." (PMID 33542243, 2021). "In a longitudinal community study assessing the relationship between chronic stress (caregiving for a spouse with dementia) and IL-6 production, it was found that caregivers′ average rate of increase in IL-6 was about four times as large as that of non-caregivers." (PMID 32235786, 2020). "IL-6 (POR = 1.59, 95%CI: 1.09–2.32) and PAI-1 (POR = 2.96, 95%CI: 1.48 to 6.85) were independently associated with more prominent ED delirium duration in subjects without dementia only." (PMID 31856187, 2019). "In conclusion, plasma IL-6, IL-8, and PAI-1 measured in the ED are associated with ED delirium duration in acutely ill older patients, but these associations were significant only in patients without pre-existing dementia." (PMID 31856187, 2019). "Highly significant positive correlation between the level of resistin and age and indices of inflammation (IL-6 and hsCRP, chitotriosidase activity) and a negative correlation with HDL-cholesterol and PON1 activity was stated in patients with all-cause dementia." (PMID 28421328, 2017).
dementia (continued). "However, our results also show that patients with DLB displayed significantly lower CSF concentrations of IL-6 than both control subjects without dementia and patients with AD." (PMID 26434635, 2015). "Since neurons do not express the IL-6 receptor, we speculate that the IL-6/IL-6R trans-signaling pathway via gp130 on neurons may be critical in mediating cognition-relevant neuronal damage, similar to what has been described in a mouse model of dementia." (PMID 34711238, 2021). "Interestingly, the brains of individuals resilient to dementia despite robust Alzheimer’s neuropathology (amyloid plaques and neurofibrillary tangles) displayed lower numbers of CD68+ microglia in the temporal lobe and higher levels of the cytokines IL-6, IL-1β, IL-1073." (PMID 32917850, 2020). "Furthermore, the correlation found between IL-6 and the CLOX2 test in patients with SSVD, but not in patients with AD, may reflect differences in the underlying inflammatory mechanisms of these two pathologically different types of dementia." (PMID 40150012, 2025). "Unexpectedly, inflammatory markers, CRP, IL-1β, IL-6, and TNF-α did not discriminate dementia cases from non-cases." (PMID 37605096, 2024). "In the present study, we did show a positive correlation of resistin with inflammatory indicators (interleukin-6 and CRP) and a negative correlation with anti-inflammatory markers (HDL-C and PON1 activity) in all dementia patients." (PMID 28421328, 2017). "The analysis showed that the log-transformed IL-6 levels were still significantly lower in patients with DLB than in patients with AD and control subjects without dementia (p < 0.001 and p = 0.006, respectively)." (PMID 26434635, 2015). "We did, however, find a significant positive correlation between log-transformed IL-6 and α-synuclein in patients with DLB (r = 0.383, p = 0.048), but not in patients with AD or control subjects without dementia." (PMID 26434635, 2015). "Our analysis showed significantly lower levels of IL-6 in CSF from patients with DLB than in CSF from patients with AD and control subjects without dementia." (PMID 26434635, 2015). "Such a scenario would be in line with our results showing decreased levels of IL-6 in patients with DLB compared with patients with AD and control subjects without dementia." (PMID 26434635, 2015). "Our first aim was to determine whether IL-6 levels are altered in patients with DLB compared with patients with AD and control subjects without dementia." (PMID 26434635, 2015). "We detected a significant negative correlation between MMSE score and log-transformed IL-6 in patients with DLB (r = −0.464, p = 0.01) and a trend to significance in patients with AD (r = −0.260, p = 0.089), but not in control subjects without dementia." (PMID 26434635, 2015). "Further, the control subjects without dementia included in our study were significantly younger than the patients with DLB and patients with AD, which is a limitation, particularly considering that previous studies have demonstrated an age-dependent increase of IL-6 levels in CSF and serum." (PMID 26434635, 2015).